IL6 (interleukin 6)
Diseases named in the same sentence as IL6 in open-access papers (continued):
Sharing a sentence is not in itself a finding about the gene and the disease.
COVID-19 (continued). "Compared with those in healthy individuals, the levels of IFN-γ, IL-12 (p70), IL-13, IL-1β, IL-2, IL-4, IL-5, IL-6, GM-CSF, IL-17A, IL-27, IFN-α, IL-15, IL-1RA, IL-7, eotaxin, GRO-α, IP-10, MCP-1, MIP-1α, MIP-1β, SDF-1α, and RANTES in mild COVID-19 patients were significantly greater." (PMID 39351097, 2024). "The increase of IL-6 in COVID-19-positive patients compared to negative ones is not as striking as in patients requiring ICU confirming that the inflammatory response to SARS-COV 2 infection is not as extreme as in severe conditions." (PMID 39582872, 2024). "Our study shows good prognostic performance of CRP and IL6 for 28-day hospitalization in patients with mild-to-moderate COVID-19, in the absence of clinical criteria for admission upon enrolment." (PMID 39664394, 2024). "The authors also investigated Th1 and Th2 cytokine dynamics in COVID-19 patients, and found that stable ratios of Th2 cytokines (IL-4, IL-6, IL-10) to IFN-γ over time indicate a dysregulated immune response, which is critical in understanding COVID-19 pathophysiology." (PMID 39518964, 2024). "U tu su svrhu korišteni Komparativna toksikogenomska baza podataka (CTD), GeneMANIA i ToppGene Suite portal te je identificirana skupina od pet zajedničkih gena (IL1B, CXCL8, IL6, IL10, TNF) za šest metala i COVID-19, koji svi kodiraju proinflamatorne i antiinflamatorne citokine." (PMID 38963144, 2024). "The analysis revealed significant associations between serum IgG levels ≥ 21.08 g/L and younger age, lower IL-6 levels, receiving ≥ 3 doses of COVID-19 vaccine, and absence of comorbidities (P < 0.05)." (PMID 39717543, 2024). "However, in contrast, when assessing interleukin-6 (IL-6) levels, PUUV and COVID-19 LDGs displayed a statistically significant elevation compared to PUUV and HC PMNs." (PMID 39011044, 2024). "Their findings underscored that severe COVID-19 cases had markedly elevated levels of NLR, Systemic Inflammation Index, and interleukin-6 (IL-6), among others, with NLR presenting an area under the curve of 0.76, indicating its efficacy in distinguishing between mild and severe cases." (PMID 39125561, 2024). "In our previous study, G-CSF, GM-CSF, IL-6, IL-8, MCP-3, MIP-1α, and VEGF were elevated in the total group of COVID-19 patients with short-term combined clinical endpoint (transfer to intensive care, high-flow oxygen therapy, lung ventilation, and in-hospital mortality)." (PMID 39497823, 2024). "In fact, the treatment strategies for acute COVID-19 and PACS could involve IL-6/IL-6 receptor-blocking agents, such as sarilumab or tocilizumab, characterized by significant beneficial properties." (PMID 39200115, 2024). "Serum S100A12 did not correlate with CRP, procalcitonin and interleukin-6 levels in the serum of patients with moderate and severe COVID-19." (PMID 39066246, 2024). "Furthermore, the researchers identified IL-6 and lactate dehydrogenase (LDH) as independent parameters for predicting the severity of COVID-19." (PMID 38287388, 2024). "This is a clear demonstration of productive SARS-CoV-2 infection of primary human macrophages and a direct association between natural infection of these cells and production of the pro-inflammatory cytokines characteristic of severe COVID-19 (CXCL9 and −10, IFNα, IL-6 and TNFα)." (PMID 39737903, 2024). "The utility of compound scores, particularly a weighted sum of IL-6, MCP, CXCL, IL-6, IL10, IL-17A, and IL-1β, were particularly stronger in predicting disease severity, reinforcing the potential of a multifaceted biomarker approach in managing COVID-19." (PMID 39062105, 2024). "Notably, the cytokine levels were significantly elevated in the COVID-19 patients compared to the control group P-values were < 0.001, 0.001, 0.008, and 0.008 for TNF-α, IL-6, IL-17, and IFN-γ, respectively." (PMID 38459174, 2024).
COVID-19 (continued). "Additionally, a correlation was observed between NGAL and IL-6, IL-12, IFN-γ, and GM-CSF—proinflammatory cytokines—and strongly chemotactic IL-8 in patients suffering from severe COVID-19." (PMID 38610616, 2024). "Nevertheless, several other clinical studies have not shown that the use of RAASI would decrease IL-6 concentrations significantly in patients with COVID-19 and cardiovascular co-morbidities." (PMID 39518552, 2024). "Others, however, suggest that a year after discharge, patients who had contracted COVID-19 did not exhibit significant differences in serum IL-6, VCAM-1, ICAM-1 or P-selectin in comparison with matched sedentary healthy controls." (PMID 38600563, 2024). "Bio-ADM and IL-6 were significantly elevated in COVID-19 patients with AKI compared to COVID-19 patients without AKI (each p < 0.001)." (PMID 38336628, 2024). "Nevertheless, COVID-19 patients with no co-morbidities had significantly higher IL-6 plasma levels than healthy controls (adjusted p = 0.018)." (PMID 39518552, 2024). "Regarding infection-related inflammatory indicators, WBC and IL-6 levels of severe COVID-19 were significantly higher than non-severe COVID-19 (P < 0.05)." (PMID 38858647, 2024). "Lastly, interleukins IL-1β, IL-6, and tumor necrosis factor plasma levels are elevated in PASC sufferers, and are also correlated to cognitive impairment in Alzheimer's disease, and with severity of hyposmia after COVID-19." (PMID 39839305, 2024). "Another study of 218 COVID-19 patients showed that the subjects with OD had slightly lower serum IL-6 levels than those without OD (3.71 vs. 6.11, p < 0.001)." (PMID 37529051, 2023). "Although a positive correlation was found between the IL-6 level and the proportion of CD56+ cells in the MS group, we did not notice any difference in the CD56+ T cell content between healthy donors and COVID-19 patients." (PMID 37240393, 2023). "Multiple and logistic regressions selected the following risk predictors for pneumonia as IL-6, CRP, obesity and for severe COVID-19 symptoms D-dimer level and a lack of targeted vaccination (p < 0.001)." (PMID 37608339, 2023). "Considering the antioxidative effect of IL-6 we aimed to establish the impact of this cytokine on tyrosine nitration and CD39 and CD73 expression patterns, using in-vitro-cultured PBMCs obtained from COVID-19 patients." (PMID 37818368, 2023). "Targeting TNF-α, IL-6, MAPK1, and MAPK3 might be potential alternative treatments for CRS and COVID-19." (PMID 36817449, 2023). "One study reviewed the medical records of 42 patients with COVID-19 compared D-dimer, fibrinogen, lymphocyte, and IL-6 levels in patients who received LMWH to those who did not." (PMID 37180701, 2023). "COVID-19 induces an inflammatory response, resulting in the release of cytokines (cytokine storm) such as tumour necrosis factor-alpha (TNF-α), and interleukins (IL-1, and IL-6)." (PMID 37347738, 2023). "IL-6 and TNF-α were higher in patients with low MBL and severe COVID-19 (p< 0.05)." (PMID 37138871, 2023). "Apart from periodontitis and COVID-19, local (salivary) and systemic (serum) TNF-α/IL-6/IL-1β levels also increased in other inflammatory conditions, such as chronic oral erosive lesions and ulcers, and these cytokine levels were inversely proportional to the IL-10 that regulated epithelial healing." (PMID 37106750, 2023). "A total of 102 intersected gene targets were obtained based on 246 active ingredient-related targets and 4829 COVID-19-related disease targets, which are possible key gene targets of the bitter almond-licorice for the treatment of COVID-19, such as IL10 and IL6." (PMID 38018195, 2023). "Similar to these studies, we also observed a significant increase in IL-6 in the plasma of severe COVID-19 and non-severe COVID-19 patients." (PMID 36851312, 2023).
COVID-19 (continued). "As expected, COVID-19 was characterized by high levels of systemic inflammation, as reflected by the acute phase reactant, CRP, which is produced by the liver in response to increased expression of IL-6." (PMID 37646024, 2023). "This experiment found that COVID-19 patients with diabetes had higher IL-6 and IFN-γ expression compared with patients without diabetes, but not mononuclear lymphocytes and their subsets." (PMID 38095633, 2023). "No statistical significance was observed when comparing the temporal differences in IL-6 levels among COVID-19 patients without disease progression." (PMID 36926338, 2023). "A previous study showed that the plasma cytokine levels such as IL-6, IL-1β, IL-10, IL-21, and TNF-α were significantly higher in asymptomatic group compared to the controls, indicating an increased inflammation in asymptomatic COVID-19 patients." (PMID 37869674, 2023). "In COVID-19 patients, normal lymphocyte counts and CRP levels were observed following the improvement in body temperature and respiratory functions after tocilizumab administration; therefore, the drug can be effective for targeting the IL-6 signaling cascade." (PMID 36677853, 2023). "Nevertheless, overall data supported the hypothesis that high IL-1β, IL-6, and TNF-α in the same patient play a role in COVID-19 and periodontitis pathogenicity independently." (PMID 37106750, 2023). "IL-6 levels in COVID-19 and ARDS non-survives and survives were 120.88 (81.09–252.58) and 81.82 (25.15–88.78), respectively." (PMID 37889917, 2023). "IL-6 plays an important role in CRS and is positively correlated with COVID-19 severity." (PMID 36835948, 2023). "COVID-19 patients with diabetes increased IL-6 and IFN-γ compared those patients without diabetes, exacerbating the increase of cytokine secretion and the deterioration of clinical outcome of COVID-19." (PMID 38095633, 2023). "Comparison of the MPO, ADA, CCL22, TNFα, and IL-6 mRNA expression between patients with and without completion of COVID-19 vaccines did not reveal any statistically significant differences." (PMID 36482706, 2023). "Using rapid extracellular antigen profiling (REAP), a group at Yale University detected enrichment of autoantibodies against IL-6 in patients with severe and moderate COVID-19 compared to people with asymptomatic infection or no infection." (PMID 37112929, 2023). "We reported that COVID-19 patients have significantly higher IL-1β and IL-6 plasma levels compared to non-COVID-19 pneumonia patients." (PMID 37986089, 2023). "IL1-RA, IL-6, IFN-γ, G-CSF, CCL-7 and VEGF serum levels could prove helpful as biomarkers to assess disease severity and the need for intensive care in COVID-19 patients." (PMID 37917760, 2023). "Levels of TNF-α, IL-1Ra, IL-6 and IL-18 were also higher in HD + COVID-19 than in HD patients, without reaching statistical significance." (PMID 36675231, 2023). "IL-6 plays a vital role in antibody synthesis, and drugs like TZB may impact immune defense against COVID-19 by affecting IL-6-mediated antibody production." (PMID 38034537, 2023). "The relationship between IL-6 and NLR and COVID-19 severity was assessed using the chi-square test." (PMID 38099004, 2023). "Moreover, p62 modulation by NSP5 and ORF3a in vitro was involved in the regulation of TNF, IL-1, IL-6, IL-10, and IL-33 mRNA expression in THP-1 monocytic cell line, indicating a proinflammatory role of this autophagy receptor in COVID-19." (PMID 37174682, 2023). "IL-6, IL-1β, and TNF-α are all key cytokines in both COVID-19 and RA." (PMID 37163438, 2023). "Regarding detection of infiltrate above median compared to infiltrate below median in COVID-19, multivariate stepwise binary logistic regression analyses adjusted for the potential confounding variables were performed separately for each DPP3, IL-6, CRP, and leucocytes." (PMID 37733154, 2023).
COVID-19 (continued). "Among them, several of the classical inflammatory markers, e.g., IL6, IL8, IL10, IL12B, TNF, and IFNγ had substantially higher levels in sepsis compared to COVID-19, leading to the conclusion that the inflammatory response is more pronounced in sepsis regardless of etiology or focus of infection." (PMID 36829233, 2023). "Significant decreases in plasma concentrations of the pro-inflammatory cytokines IL-6, TNF, and IFN-γ, the leukocyte chemoattractants CXCL8, CXCL10, and CCL2, and the anti-inflammatory cytokines IL-10 and IL-1Ra were observed in COVID-19 patients during dexamethasone treatment." (PMID 37614228, 2023). "This study aims to investigate the levels of Ang1 and Ang2 in COVID-19 patients during the course of hospitalization, and correlate the levels according to the severity of illness, anti-SARS-CoV-2 IgG titers, interleukin IL-6 level, and clinical outcome." (PMID 38138084, 2023). "We identified nine GO terms associated with the pathway, which could result in upregulation of inflammatory cytokines, such as IL-6 and TNF-α, and contribute to severe cardiac and pulmonary injury in COVID-19 patients." (PMID 38065980, 2023). "Furthermore, targeting IL-6 and IL-10 has been proposed for treating ARDS in COVID-19 patients based on its immunoregulatory functions." (PMID 38249419, 2023). "Although in vitro studies showed that remdesivir reduced IL-6 production induced by human coronavirus OC43 in human lung fibroblasts, little is available on the effect of remdesivir on the inflammatory response in clinical studies on COVID-19." (PMID 37896877, 2023). "The mediators CCL3, CCL4, CCL2, CCL5, IL-12, IL-15, IL-1Ra, and PDGF were higher in healthy volunteers, while the mediators CCL11, CXCL10, IL-1b, IL-6, TNF-a, IFN-g, IL-17, IL-9, IL-10, IL-13, FGF-basic, G-CSF, GM-CSF, IL-7, and IL-2 were increased in COVID-19 positive patients." (PMID 37903875, 2023). "When the anti-IL-6 antibody was used as the recognition molecule, the detection ability of the SiNW-FET could distinguish only severe COVID-19-infected patients with a high-level expression of IL-6." (PMID 36679421, 2023). "Pro-inflammatory IL-6 could be involved in the alteration of Leydig cell differentiation as increased LH levels and decreased T/LH and FSH/LH ratios were found in COVID-19 patients compared to healthy." (PMID 35943723, 2023). "During the COVID-19 phase, IL1β and IL6 increased by day 90 in Group I, while there was no significant change in Group II." (PMID 37546047, 2023). "Most of them were higher in COVID-19 individuals, although all of them except IL-6 levels were not statistically significant." (PMID 37363608, 2023). "However, the clinical guideline already includes IL-6 inhibitor, a key TH17 initiator, to treat COVID-19 with complications." (PMID 36914565, 2023). "However, most of the included studies indicated elevated serum pro-inflammatory cytokine (IL-1β, IL-6 and TNF-α) levels in diseases (COVID-19/periodontitis) compared to healthy controls included in the same study." (PMID 37106750, 2023). "In a recent study comprising 150 patients of COVID-19 in Wuhan, China, higher levels of ferritin and IL6 were observed in the non-survivors compared to the survivors." (PMID 36992366, 2023). "IL-6, CRP, ferritin, LDH, and D-dimer were increased in all COVID-19 forms." (PMID 37239895, 2023). "Among the cytokines analyzed in response to S-peptide, some of them such as TNFα, IL-6, IL-2, IFNγ, or CXCL10 were differentially produced between naïve subjects and subjects recovered from COVID-19 early after the second vaccination dose (sample 2), with higher levels in the former group." (PMID 37153580, 2023). "In fact, patients who did not survive COVID-19 had higher levels of IL-6 than those who did survive." (PMID 37180105, 2023). "Interestingly, IL-6 induced AAT and tocilizumab (an IL-6R antagonist) down-regulated AAT in COVID-19." (PMID 37294003, 2023).
COVID-19 (continued). "None of the early COVID-19 treatments were effective in reducing levels of IL-6, a major component of the cytokine storm." (PMID 37998327, 2023). "The data suggested that the patients with CR or near-CR receiving low-dose GCs maintenance therapy had milder COVID-19 symptoms, higher quality of life, and lower IL-6 levels as compared to those who did not receive GCs therapy." (PMID 38274101, 2023). "This study aimed to address the level of three cytokines which were interleukin-1-beta (IL-1β), interleukin-6 (IL-6), and tumour necrosis factor-alpha (TNF-α), with different blood parameters to the formation of cytokine storm or any complication among COVID-19 patients." (PMID 37363608, 2023). "D-dimer, CRP, IL-6, LDH, and procalcitonin levels increased from mild to severe COVID-19." (PMID 37016651, 2023). "Eleven articles that did not relate to long COVID-19 or with an IL-6 value not provided were excluded." (PMID 37095536, 2023). "Serum IL-6 levels and NLR are positively correlated with COVID-19 severity." (PMID 38099004, 2023). "DPP3 was significantly elevated in COVID-19 patients (median 20.85 ng/ml, 95% CI 18.34–24.40 ng/ml), as opposed to those without SARS-CoV-2 (median 13.80 ng/ml, 95% CI 11.30–17.65 ng/ml; p < 0.001, AUC = 0.72), opposite to IL-6, CRP (each p = n.s)." (PMID 37733154, 2023). "Studies have documented significant elevation of inflammatory cytokines TNF-α, IL-6 in severe COVID-19 patients compared to non-severe cases." (PMID 38057707, 2023). "In addition, our previous longitudinal analysis of cytokine profiles in mild to critical COVID-19 patients revealed that cytokines such as IL10, CXCL9, CXCL10, and IL6 progressively increased with greater disease severity." (PMID 36798115, 2023). "Of the upregulated inflammatory cytokines, IL-6 has been considered as a key cytokine involved in the cytokine storm triggered by COVID-19 and given the high levels of this cytokine induced by SARS-CoV-2, IL-6 blocking agents have been used for treating severe COVID-19." (PMID 37935729, 2023). "In COVID-19, neutrophils contribute to disease pathogenesis by producing pro-inflammatory cytokines like TNF-α and IL-6 that contribute to lung-centric and systemic cytokine storms and the chemokine CXCL8 to promote further neutrophil recruitment and augment inflammation." (PMID 38139412, 2023). "COVID-19 patients with diabetes had higher levels of IL-6 and IFN-γ than those patients without diabetes." (PMID 38095633, 2023). "In the final multivariate regression analysis, three predictors of poor COVID-19 outcome, namely MAFLD (odds ratio (OR) 3.4, 95% confidence interval (CI) 3.0–6.3; p < 0.001), BMI (OR 2.3, 95% CI 1.7–3.1; p = 0.045), and IL-6 (OR 2.1, 95% CI (1.2–2.3); p = 0.03), remained significant." (PMID 37629728, 2023). "During the COVID-19 phase, both IL1β and IL6 increased significantly at day 90 in Group I and showed no significant change in Group II." (PMID 37546047, 2023). "IL-6, TNF-α, and IL-10 may especially be related to cytokine storms in neonates of mothers with COVID-19." (PMID 36979888, 2023). "Serum IL-6 levels and NLR are strongly correlated with COVID-19 severity." (PMID 38099004, 2023). "Severe COVID-19 and advanced age are both correlated with biomarkers of systemic inflammation, such as the neutrophil/leukocyte ratio (NLR), weaker type-I IFN responses, NLRP3 inflammasome activation, and IL-6, IL-12 and IL-1β secretion." (PMID 36680215, 2023). "Increased levels of IL-6 were observed in COVID-19 non-survivors; however, this was not significant." (PMID 36509969, 2023). "In severe, but not critical COVID-19 patients, we found that plasma Leptin, Resistin and IL-6 correlated with the fraction of inspired oxygen (FiO2) but not the length of hospital stay." (PMID 36509969, 2023). "This evidence suggests that in non-complicated COVID-19 cases, IFNγ can halt excessive IL-6 production." (PMID 37759738, 2023).